SLC39A10 (solute carrier family 39 member 10)
Description:
Zinc-influx transporter. When associated with SLC39A6, the heterodimer formed by SLC39A10 and SLC39A6 mediates cellular zinc uptake to trigger cells to undergo epithelial-to-mesenchymal transition (EMT). SLC39A10-SLC39A6 heterodimers play also an essential role in initiating mitosis by importing zinc into cells to initiate a pathway resulting in the onset of mitosis. Plays an important for both mature B-cell maintenance and humoral immune responses (By similarity). When associated with SLC39A10, the heterodimer controls NCAM1 phosphorylation and integration into focal adhesion complexes during EMT (By similarity).
Synonyms: KIAA1265; ZIP10; FLJ90515; DKFZp564L2123; LZT-Hs2
Tractability: Antibody: UniProt places it where antibodies can reach, with high confidence; its Gene Ontology location is reachable by antibodies, with high confidence; UniProt predicts a signal peptide or a membrane-spanning region; the Human Protein Atlas places it where antibodies can reach. PROTAC: ubiquitination databases record sites on it; its protein half-life has been measured.
Gene: Protein-coding gene on chromosome 2 (195,575,977 to 195,737,706, forward strand). Ensembl gene ENSG00000196950.
Subcellular location: Cell membrane; Apical cell membrane
Subcellular location (Human Protein Atlas): Cytosol; Nucleoplasm; Plasma membrane
Pathways (Reactome):
Transport of small molecules: Zinc influx into cells by the SLC39 gene family
Gene Ontology:
Molecular function: protein binding; zinc ion transmembrane transporter activity; monoatomic cation:bicarbonate symporter activity; metal ion transmembrane transporter activity; protein tyrosine phosphatase activator activity
Biological process: epithelial to mesenchymal transition; zinc ion transmembrane transport; intracellular monoatomic cation homeostasis; zinc ion import across plasma membrane; bicarbonate transport; metal ion transport; transmembrane transport
Cellular component: apical plasma membrane; plasma membrane; membrane
Genetic constraint (gnomAD): Loss-of-function variants: 11 observed, 55.52 expected, observed/expected ratio (o/e) 0.2, 90% interval 0.12 to 0.33. The upper end of that interval is the gene's LOEUF score, 0.33, which puts it in group 1 of 6, group 1 being the genes least tolerant of losing a copy. Missense variants: 809 observed, 1,028.6 expected, observed/expected ratio (o/e) 0.79, 90% interval 0.74 to 0.83. Synonymous variants: 311 observed, 351.35 expected, observed/expected ratio (o/e) 0.89, 90% interval 0.81 to 0.97.
Homologues: Orthologues: chimpanzee SLC39A10 (99% identical), macaque SLC39A10 (99% identical), dog SLC39A10 (93% identical), pig SLC39A10 (93% identical), rabbit SLC39A10 (92% identical), mouse Slc39a10 (87% identical), rat Slc39a10 (87% identical), guinea pig SLC39A10 (82% identical), zebrafish slc39a10 (47% identical), Drosophila melanogaster foi (25% identical). Paralogues in human: SLC39A6 (33% identical), SLC39A5 (23% identical), SLC39A12 (19% identical), SLC39A14 (19% identical), SLC39A4 (18% identical), SLC39A8 (17% identical).